INS (insulin)
Diseases named in the same sentence as INS in open-access papers (continued):
Sharing a sentence is not in itself a finding about the gene and the disease.
type 2 diabetes (continued). "Fourteen per cent of participants with a clinical diagnosis of insulin-treated type 2 diabetes had rCP < 200 pmol/l." (PMID 28983693, 2018). "Instead, insufficient insulin secretion in type 2 diabetes has been attributed to beta cell dysfunction due to various mechanisms, including de-differentiation." (PMID 29185012, 2018). "The pharmacodynamic (PD) properties of the widely used basal insulin analogs detemir and glargine have been extensively studied in patients with type 1 and to a lesser extent in those with type 2 diabetes." (PMID 30114246, 2018). "Type-2-diabetes is a metabolic disorder characterized by hyperglycemia resulting from decreased secretion of insulin due to pancreatic β-cell dysfunction and resistance of peripheral organs to available insulin." (PMID 29700330, 2018). "Autophagy in adipose tissue (AT) has also been explored in connection to type 2 diabetes as an additional key target of insulin." (PMID 30190661, 2018). "During the treatment of type II diabetes, DNJ can be used alone or in combination with insulin secretion or sensitizing agents depending on the cause and existing metabolic disorders." (PMID 30131712, 2018). "As such, impaired skeletal muscle insulin action and glucose utilization are the primary defects in the development of type 2 diabetes." (PMID 28688083, 2018). "Significantly reduced resting metabolic flux through the TCA cycle and oxidative phosphorylation were reported in skeletal muscle of patients with type 2 diabetes and insulin resistant offspring of type 2 diabetic patients." (PMID 29315239, 2018). "The safety and efficacy of teneligliptin 20 mg in Japanese patients with type 2 diabetes has been demonstrated both as monotherapy and in combination with pioglitazone, glimepiride, insulin, and canagliflozin." (PMID 29435909, 2018). "Observational study of once-daily insulin detemir in people with type 2 diabetes aged 75 years or older." (PMID 29527102, 2018). "Overall, these results suggest that the DID-EQ would be a useful tool in studies examining the patient experience with non-insulin injectable medications for type 2 diabetes." (PMID 30294714, 2018). "Patients with type 2 diabetes who initiated basal insulin between 2004 and 2011 were eligible for inclusion." (PMID 30226870, 2018). "In type-II diabetes, increased plasma lipid profile leads to increased free fatty acid (FA) levels, because of inability of insulin to suppress the hormone sensitive lipase in the adipose tissue and the secretion of very low-density lipoproteins in the liver." (PMID 30023334, 2018). "In participants with insulin-treated type 2 diabetes, self-reported hypoglycaemia was approximately twice as common in those with rCP < 200 pmol/l compared with those with rCP ≥ 200 pmol/l." (PMID 28983693, 2018). "Insulin secretion was lower in patients with type 1 diabetes than in patients with type 2 diabetes or healthy individuals." (PMID 30159333, 2018). "Previous studies have suggested that insulin therapy is viewed as the most burdensome treatment modality among people with type 2 diabetes." (PMID 29347915, 2018). "In the DEVOTE study (Efficacy and Safety of degludec versus glargine in type 2 diabetes), 7637 patients with type 2 DM were randomized to receive either insulin degludec or insulin glargine U100." (PMID 28725272, 2017). "miR-29a expression was up-regulated in the serum of patients with type 2 diabetes and in 3T3-L1 adipocytes cultured with high insulin and high glucose." (PMID 28427228, 2017). "There are limited data on the effects of insulin on lipoprotein subclasses in type 1 or type 2 diabetes." (PMID 28587667, 2017). "There have been a number of studies using low-carbohydrate, high-fat dietary strategies in the management of type 2 diabetes, but these group sizes have been small and often excluded subjects taking insulin." (PMID 30291062, 2017).
type 2 diabetes (continued). "GLP-1-based clinical therapies have firmly established their importance among the therapeutical approaches available for the treatment of type 2 diabetes; their action is exerted by potentiating glucose-stimulated insulin secretion." (PMID 28704555, 2017). "Type 2 diabetes (T2D) is developed when pancreatic beta cells fail to secrete sufficient amounts of insulin to meet the metabolic demand due to insulin resistance." (PMID 29018279, 2017). "Type 2 diabetes results from the interplay of systemic insulin resistance of peripheral tissues, insufficient insulin secretion from pancreatic beta cells, and insufficient beta cell mass due to genetic and environmental factors." (PMID 29214024, 2017). "Protein tyrosine phosphatase 1B (PTP1B), a negative regulator of insulin and leptin signaling pathways, is a promising target for the development of type 2 diabetes treatment." (PMID 29441120, 2017). "Intraperitoneal injections of mGLP-1 into streptozotocin (STZ)-induced type 2 diabetic mice significantly reduced blood sugar levels and stimulated insulin secretion." (PMID 28152036, 2017). "The study population includes women with type 1 or type 2 diabetes, who are pregnant and being treated with insulin." (PMID 28100192, 2017). "All these findings suggest that disruption of the Prep1/p160 molecular interaction enhances insulin sensitivity impaired by ceramides in skeletal muscle cells and indicate this complex as an important target for type 2 diabetes." (PMID 29069751, 2017). "Type 2 diabetes is a devastating disease that requires constant patient self-management of glucose, insulin, nutrition and exercise." (PMID 28448498, 2017). "In a subgroup of patients with type 2 diabetes, a decrease in fasting insulin (MD −7 μU/ml, 95% CI −11.5, −2.5) was observed." (PMID 28536448, 2017). "Taken together, we found hemin can improve lipid metabolism and insulin sensitivity in cultured hepatocytes, and oral administration of hemin can improve lipid metabolism and insulin sensitivity in a diet-induced type 2 diabetes model." (PMID 28933767, 2017). "The increased number of patients with type 2 diabetes (T2D) has become a worldwide problem, and insulin sensitizers such as thiazolidinediones (TZDs) are used as therapeutic agents." (PMID 29165364, 2017). "In the same way, Goto-Kakizaki rats (a non-obese T2D animal model), which have a defect at the IDE gene, as well as some type 2 diabetic patients, exhibit reduced insulin clearance and augmented plasma insulin concentrations prior to the onset of T2D17,18." (PMID 29093479, 2017). "The proportion of variation explained by all of the variants that we used as instrumental variables for the potential mediators varied from 1.2% (for fasting insulin) to 5.7% (for type 2 diabetes)." (PMID 28889241, 2017). "In cases of type 2 diabetes, only minor changes in insulin profile have been reported after GB, whereas after SG or RYGB, an improved initial insulin response has been described that is reminiscent of that in glucose-tolerant obese people [83•]." (PMID 28780756, 2017). "Whitening and severely impaired insulin-stimulated glucose uptake in BAT was confirmed in a rat model of type-2 diabetes." (PMID 29196742, 2017). "Similar findings have been reported for once-daily liraglutide, which significantly increased both first- and second-phase insulin secretion after 14 weeks of treatment in participants with type 2 diabetes." (PMID 28526920, 2017). "Concerning quality of life, previous studies revealed a lower QoL in patients with type 1 diabetes or insulin-treated type 2 diabetes and in subjects with one or more late diabetic complications." (PMID 29062603, 2017). "In our study, younger insulin-treated type 2 diabetics experienced more hypoglycemic episodes, which is contrary to some other studies." (PMID 28913365, 2017). "The aim of the study was to investigate the relationship between insulin sensitivity and the QTc interval in patients with type 2 diabetes." (PMID 28912840, 2017).
type 2 diabetes (continued). "Insulin-treated patients had higher glycated hemoglobin A1c, more premorbid insulin-requiring type 2 diabetes, and greater blood glucose levels but lower c-peptide levels on admission." (PMID 28497374, 2017). "GLP-1 functions to delay gastric emptying, stimulate insulin secretion and mediate satiety in the central nervous system (CNS), all actions that are beneficial to individuals with obesity and type 2 diabetes." (PMID 28733905, 2017). "The insulin-related biomarkers, including QUICKI, HOMA-IR, HOMA-β, and DI were calculated to reveal the health of insulin-producing cells and function of insulin in type 2 diabetes." (PMID 28348972, 2017). "Although the occurrence of hyperglycemia is inevitable in Type 1 diabetes as well as late stage of Type 2 diabetes, exogenous insulin is still the gold standard for these diabetic patients." (PMID 28594910, 2017). "Our data show that the mode of insulin sensitization by Vps34 inhibition has similarities to that of Metformin, the most frequently prescribed drug for Type-2 diabetes, but acts through a distinct primary mechanism of action." (PMID 29180704, 2017). "Glitazones are known for their antidiabetic action and belong to a group of synthetic compounds which act as agonists of PPARγ and improve insulin sensitivity and reduce the blood glucose levels in patients with type 2 diabetes." (PMID 28656106, 2017). "Whereas the majority (83.3%) reported type 2 diabetes, 57.5% were treated with insulin and/or other anti-diabetic injection." (PMID 28882117, 2017). "In this study, we revealed that insulin treatment significantly attenuated the decline of skeletal muscle mass in patients with type 2 diabetes." (PMID 28246927, 2017). "As expected, participants with type 2 diabetes had significantly higher blood glucose, HbA1c, c-peptide and fasting insulin than controls and obese participants." (PMID 28752059, 2017). "Data from the Center for Disease Control and Prevention show that between 2007 and 2009, 26% of patients with type 2 diabetes were receiving insulin therapy." (PMID 28666031, 2017). "In this regard, the intravenous infusion of insulin leads to the suppression of IL-4 expression in mononuclear cells from obese patients with type 2 diabetes." (PMID 28696379, 2017). "The insulin sensitivity and insulin secretion, known as the disposition index (DI), was impaired after induction of type 2 diabetes and this parameter showed a significant decrease in diabetic mice as compared to other groups (p<0.05)." (PMID 28348972, 2017). "Currently, targeting of the inflammasome is considered a clinically efficacious strategy in restoring insulin action in humans with type 2 diabetes." (PMID 28761623, 2017). "Mainly seen as an indicator for impaired β-cell function, proinsulin can be detected at low concentrations in the blood of healthy persons but is found at higher concentrations in the blood of insulin-resistant subjects and patients with type 2 diabetes." (PMID 28468307, 2017). "Recent study reported improved insulin sensitivity and reduced total cholesterol and triglycerides as well as reduced C-reactive protein and prostaglandin E2 in patients with type 2 diabetes." (PMID 28729836, 2017). "Type II diabetes is a complex clinical syndrome, depicted by persistent hyperglycemia in the setting of decreased insulin secretion and sensitivity, which results in a compilation of aberrant metabolic changes." (PMID 29163354, 2017). "As a consequence of the improvement in insulin sensitivity, PPARγ activation by thiazolidinediones decreases glycated hemoglobin (HbA1c) and lowers the glucose and insulin levels in patients with type 2 diabetes." (PMID 28656106, 2017). "The glucagon-like peptide-1 receptor (GLP-1R) is a key therapeutic target in the management of type II diabetes mellitus, with actions including regulation of insulin biosynthesis and secretion, promotion of satiety, and preservation of β-cell mass." (PMID 28283573, 2017).
type 2 diabetes (continued). "Considering these premises, the purpose of the present study was to validate the Italian version of the DEPS-R scale in a sample of insulin-treated male and female subjects with type 1 and type 2 diabetes aged from 13 to 55 years." (PMID 28724422, 2017). "Glipizide is a second-generation oral hypoglycemic medicine developed in the 1950s for the cure of type II diabetes because of its capability to particularly stimulate insulin secretion from β-cells." (PMID 29245957, 2017). "Troglitazone are used in the cure of type II diabetes to reduce blood glucose levels and improve the sensitivity of an amount of tissues to insulin." (PMID 28460464, 2017). "In this research, we investigated the impact of physical activity on the glycemic control of patients with type 1 and type 2 diabetes, as well as its correlation with other oral treatment options/insulin." (PMID 29910418, 2017). "The “synergistic effect” is thus less pronounced in patients with type 2 diabetes than in those with type 1 diabetes due to the less use of exogenous insulin for glucose lowering at least at the initiation of treatment." (PMID 29017477, 2017). "Even type 2 diabetes patients receiving the highest dose, presented only a trend to an increased insulin sensitivity-index (ISI) and a rise in secondary bile acid (deoxycholin acid)." (PMID 29286343, 2017). "In type 2 diabetes mellitus (T2D), the inability of the body to maintain glucose homeostasis stems from a combination of insulin resistance and beta-cell dysfunction." (PMID 28663594, 2017). "Type 2 diabetes is a group of metabolic disorder characterized by hyperglycemia dyslipidemia, and protein metabolism due to insulin resistance, impaired insulin signaling, and β-cell dysfunction." (PMID 28230764, 2017). "Recent population study identified 2-hydroxybutyric acid as an early metabolic marker of type 2 diabetes by inhibiting the release of insulin from β-cells." (PMID 28900617, 2017). "A study conducted by Jellis showed that lower post-contrast T1 values were observed in patients with type 2 diabetes with abnormal insulin sensitivity." (PMID 28338005, 2017). "In type-2 diabetic (T2D) subjects, hyperglycemia is largely the consequence of insufficient insulin secretion and excessive glucagon secretion in a context of insulin resistance." (PMID 28887444, 2017). "Recent studies suggested the presence of immature, Ucn3-negative and insulin-positive cells in the islets from donors with type 2 diabetes." (PMID 28939870, 2017). "Type 2 diabetes is characterized by insulin tolerance in target cells followed by a reduction of pancreatic β-cell mass." (PMID 29070797, 2017). "Impaired suppression of glucagon by insulin and glucose have been proposed as potential mechanisms for the hyperglucagonemia observed in individuals with type 2 diabetes (T2DM)." (PMID 28881681, 2017). "A Cochrane review analysis showed no clinical difference in the safety and efficacy for insulin glargine and insulin detemir in the treatment for type 2 diabetes." (PMID 28970434, 2017). "Impaired insulin-stimulated PI3K activity was observed in type II diabetes patients and in cultured fibroblast cells that were subjected to severe insulin resistance." (PMID 28801592, 2017). "Changes in insulin secretion, insulin sensitivity, and cardiometabolic traits during the follow-up period and the incidence of type 2 diabetes, hypertension, CVD events, and total mortality." (PMID 28911155, 2017). "TZDs are potent insulin-sensitizers and certain TZDs represent a therapeutic target for the treatment of type 2 diabetes." (PMID 28298922, 2017). "For chlorpropamide, a sulfonylurea to increase the secretion of insulin to treat type 2 diabetes, there are few reports about its anti-inflammatory effects." (PMID 28924171, 2017). "For this, cultured mouse renal mesangial cells were exposed to conditions simulating type 2 diabetes (high glucose and insulin)." (PMID 28894214, 2017).
type 2 diabetes (continued). "SGLT2 inhibitors have established application in the treatment of type 2 diabetes in COPD and potential application as an insulin adjunct in the treatment of the insulin‐deficient diabetes seen in CF." (PMID 28192604, 2017). "Type 2 diabetes is a disorder resulting from the abnormal secretion or functioning of the key hormone, insulin, which regulates both the biosynthesis of glucose in the liver, as well as glucose utilization by peripheral muscles and fat tissue." (PMID 28758947, 2017). "Our findings in the present study are in concert with our previous observation in patients with type 2 diabetes that glucagon secretion concomitantly decreases with insulin secretion." (PMID 29162828, 2017). "At 9 years, less than 25% of patients are able to control their blood glucose level with only one medication, and 10-15 years after the diagnosis of type 2 diabetes, more than 50% of patients will require insulin." (PMID 30291062, 2017). "The top 20 most significant enriched pathways included pathways in cancer, insulin signalling pathway, type 2 diabetes and mTOR signalling." (PMID 28643459, 2017). "Once β-cells fail to compensate for insulin resistance, hyperglycemia and type 2 diabetes ultimately occurs." (PMID 28842702, 2017). "eQTL SNP-gene pairs for obesity and type 2 diabetes showed evidence for significant epistatic interactions within the glucose-insulin and leptin signaling pathways." (PMID 29081791, 2017). "Specifically, in obesity‐related diseases such as type 2 diabetes, FFAs directly reduce insulin sensitivity and glucose uptake in skeletal muscle." (PMID 27619557, 2017). "Type 1 and type 2 diabetes (T2D) are characterized by a reduced insulin secretion from the pancreas, due to shortage of β-cells and decreased β-cell function." (PMID 28729853, 2017). "Even though hypoglycemia is more common in type 1 diabetes, it continues to remain an important complication of insulin treatment in type 2 diabetes." (PMID 28913365, 2017). "Levitt and colleagues reported observational data from South Africa; in their extensive study, women with pregestational type 2 diabetes were treated with insulin or oral glucose-lowering agents before and during pregnancy." (PMID 28770325, 2017). "T1D and type-2 diabetes (T2D) can be differentiated by quantifying the presence of ketones or testing the presence of autoantibodies specific to insulin." (PMID 28149833, 2017). "Together with metabolic disruptions in insulin signaling, this manifestation of immune dysfunction common to obesity and type 2 diabetes present a favorable environment for cancer cell proliferation, invasion, and survival." (PMID 29238337, 2017). "We consider this collaboration essential for not only designing and conducting research study that is responsive to the needs and practical question non-insulin treated type 2 diabetes patient’s and caregivers daily but also to disseminating our findings." (PMID 28545493, 2017). "Type 2 diabetes is the most frequent type of the disease; it is characterized by a defect in the secretion of insulin and resistance in its target organs." (PMID 29261102, 2017). "Despite extensive research on DHEA and insulin action, information about the role of DHEA in type 2 diabetes risk remains scarce." (PMID 27771738, 2017). "In human, young, normoglycemic and insulin-resistant offspring of parents with type 2 diabetes showed impaired muscular signaling with enhanced intramyocellular lipid content." (PMID 28078101, 2017). "Earlier studies have reported enhanced protein and gene expression of B1R in vessels and peripheral organs of STZ-diabetic rats and in models of type 2 diabetes and insulin resistance." (PMID 29163205, 2017). "Type 2 diabetes is the most frequent form of the disease; it is characterized by a defect in the secretion of insulin and a resistance in its target organs." (PMID 29261102, 2017).